TNF (tumor necrosis factor)
Diseases named in the same sentence as TNF in open-access papers (continued):
Sharing a sentence is not in itself a finding about the gene and the disease.
infection (continued). "HIV-1∆Vpr-infected MDMs exhibited reduced infection over time and specifically a significant downregulation of IL-1β, IL-8 and TNF-α at the transcriptional and/or protein levels compared to HIV-1wt-infected cultures." (PMID 22727020, 2012). "And had an inflammatory profile on the seventh day after infection to be held the balance between cytokines TNF-α/IL-10." (PMID 22412949, 2012). "During the initial stages, TNF acts primarily as an alarm cytokine alerting surrounding cells to the presence of an infection." (PMID 22545059, 2012). "The initial response of the immune system is triggered by an infection or other offending agent and involves the release of molecules such as cytokines (IL-12, TNF-α, IL-1) and acute phase proteins." (PMID 22969267, 2012). "Systemic infection of mice with L. monocytogenes leads to recruitment of CCR2+ monocytes via CCL2, into the spleen where they differentiate into TNF- and inducible NO synthase (iNOS)-producing DCs that are essential for control of the infection." (PMID 22383883, 2012). "The accumulation of IL-6 and TNF commenced as early as 1 day after infection with their concentrations increasing with increasing concentrations of C. trachomatis." (PMID 22529524, 2012). "Infection of unprimed or RANKL-primed RAW-D cells with P. gingivalis stimulated the expression of TNF-α." (PMID 22723864, 2012). "Studies have also revealed that TNF-α is expressed in MTB-infected tissues during the whole latent phase of infection, suggesting a contribution, with other cytokines like IFN-γ, in the control of the bacillus multiplication." (PMID 23251798, 2012). "Determination of IL-6 and TNF alpha in blood samples and homogenates of the cerebellum 30 hours after infection revealed that the protein expression of IL-6 was much higher in both compartments in comparison to TNF alpha." (PMID 22781194, 2012). "Relatively high levels of TNFα, IFNγ, IL-1, IL-6 were recorded at the early stage of infection and persisted throughout." (PMID 23323093, 2012). "In this study, we demonstrate that flagella produced by Cronobacter species stimulate the activation of IL-8 and TNF-α in an infection model using human macrophages." (PMID 23284883, 2012). "Kinetics studies revealed that live C. trachomatis induced TNF, IL-6, and IL-8, as a function of time, with day-2 infection inducing the highest cytokine levels." (PMID 22529524, 2012). "In response to infection, macrophages secret TNF-α and IL-12, which drives NK cells to produce IFN-γ." (PMID 24049654, 2012). "Confocal microscopy confirmed a more intense deposition of TNF-α both in cortex and medulla of thymic lobules after infection." (PMID 22461911, 2012). "Further, BP-induced significantly higher levels of pro-inflammatory cytokine secretion from ATII cells (IL-6, IL-8) and macrophages (IL-6, TNFα) at 6 h post-infection compared to BM (p < 0.05)." (PMID 23293773, 2012). "Maximum IL-6 and TNF levels were observed at 2 days after infection and remained steady thereafter up to 4 days after infection, suggesting a complex interaction exists between C. trachomatis and macrophages." (PMID 22529524, 2012). "IL-1 and TNF-α have been shown to be produced by either the binding of gp120 to the CD4 molecules on mononuclear phagocytes or infection with HIV." (PMID 22242038, 2012). "Biologic agents (TNFα antagonists) should be stopped pre-operatively due the increased infection rate." (PMID 22697352, 2012). "IL1β, IL6, IL12 and TNFα act proinflammatory and are known to be secreted by activated microglia in many different conditions, such as neurodegenerative disease, trauma or infection." (PMID 22647544, 2012). "The levels of IL-1ß, IL-6, IL-12, and TNF-alpha in mice sera were measured over the first 4 days after infection with Lm, L.inn, and the L.inn::vgc strain." (PMID 22536395, 2012). "As such, the contribution of Eap to stimulation of TNFα production very likely occurs during a different phase of the infection to cytolytic toxins." (PMID 22905199, 2012).
infection (continued). "Of note, a large proportion of these PLs comprised of monocyte-macrophage like cells and FV3 infections also elicited significantly increased expression of the macrophage pro-inflammatory genes (TNFα and IL-1β) in the PL populations." (PMID 22852041, 2012). "Four animals were sacrificed 2, 4, 7, 10, 16, and 21 days after infection to obtain the serum for cytokines quantification (TNF, IFNγ, and IL-10)." (PMID 22666132, 2012). "At late infection in mice suffering of progressive disease, an exacerbation of cytokine release was observed such as in memTNFΔ1–12 KI and TNF−/− mice whereas memTNFΔ1–9,K11E KI mice exhibited normal or attenuated responses." (PMID 22666310, 2012). "The levels of myeloperoxidase (as neutrophil marker), TNFα, INFγ, GM-CSF, IL-1β and IL-6 transiently increased in lungs after infection, while levels of IL-10, IL-17A and IL-22 were indistinguishable from PBS controls." (PMID 22319619, 2012). "Confocal microscopy data showed that co-localization of TNF-α and fibronectin was increased after infection." (PMID 22461911, 2012). "In vivo anti-TNFα antibody administration of C57BL/6 mice one day before infection and every day thereafter resulted in a significant reduction in neutrophil recruitment 3 days after administration of 12500 EID50 PR8." (PMID 22496659, 2012). "IFN-γ as well as members of the TNF superfamily such as LT-α and TNF are produced in large amounts during infection and play important roles in the activation of the vascular endothelium." (PMID 23300435, 2012). "IFN-γ and TNF-α are produced systemically and locally during this infection and limit viral replication and dissemination." (PMID 22880122, 2012). "T lymphocytes use their TCR as a pattern recognition receptor to sense the presence of infection and produce after activation proinflammatory cytokines such as TNF-alpha." (PMID 22935149, 2012). "Airway levels of CXCL1, CCL2, CCL3, CCL5, IFNγ, IL-6, and TNFα were measured 3 and 6 days after infection." (PMID 22496659, 2012). "At times during severe disease in FVB mice (day 6–8 post-infection), increased levels of systemic TNF-α were found compared to C57BL/6 mice." (PMID 23300439, 2012). "Despite the anti-TNF group having a six times higher rate of smoking, they still exhibited similar wound healing and infection complication rates." (PMID 23251815, 2012). "The results presented here thus provide a framework for dissecting the cell type-specific role of NFATp and its upstream signal transduction pathways in the regulation of inflammatory response genes in general, and TNF in particular, involved in MTb infection." (PMID 22844476, 2012). "The levels of the chemokines KC, MIP-1α, MIP-2, and the pro-inflammatory cytokines IL-1β, IL-6 and TNFα further increased and peaked at day 2 of infection." (PMID 22347396, 2012). "For example, the TNF-α response, which is essential for infection control, is triggered by several microbial PAMPs of a sole pathogen through their specific TLRs." (PMID 22745710, 2012). "At day 7 post-infection, IFNγ and TNFα were significantly more elevated in cecal and blood, respectively, in A2AAR-/- mice than wild-type mice indicating that onset and resolution of inflammation were both delayed in the absence of A2AARs." (PMID 23217055, 2012). "In summary, we identify a new biological role for the ie1 gene of MCMV involving the regulation of pro-inflammatory cytokines, especially TNFα production, in both in vitro and in vivo infections." (PMID 22952450, 2012). "TNFα also shares a significant role in resistance because TNFα −/− mice readily succumb to infection with Leishmania species." (PMID 21912560, 2012). "A crosstalk between pMφ, γδ T cells, and neutrophils has been found to be involved in augmented TNFα expression and production during infection." (PMID 22481867, 2012).
infection (continued). "In contrast, the SIV KVA10 tetramer+ CD8 T cells almost completely lose the ability to produce IFN-γ and TNF-α after low levels of antigen stimulation by day 14 and this is maintained through day 49 of infection." (PMID 22403659, 2012). "For the RNA expression studies, MCMV induces TNFα production in an acute infection, and it is understood that TNFα levels positively correlate with the level of infection." (PMID 22952450, 2012). "Children with asymptomatic P. falciparum infections have elevated plasma IFN-γ, TNF and IL-4 levels, whilst a cross-sectional study of third trimester pregnancies reported increased G-CSF and IL-10 in women with asymptomatic infections." (PMID 23155405, 2012). "To further determine the role of these cytokines on the impact of Vγ9Vδ2 T cells in Brucella-infected DCs, we performed infection experiments in the presence of blocking anti-TNF-α or anti-IFN-γ mAbs." (PMID 22928003, 2012). "Further, virus-infected young mice secrete significant amounts of proinflammatory cytokines and children who have recovered from natural infections secrete significant levels of TNF-α." (PMID 22642811, 2012). "TNFα levels after infection were measured in the different organs from viral-infected and mock-infected mice." (PMID 22952450, 2012). "The exact mechanism by which cytokine TNF-α contributes to protection from infection by Legionella spp." (PMID 23092579, 2012). "In contrast, all strains induced significant amounts of IL-β and TNF-α in THP-1 cells in an infection time of 1 h." (PMID 22558404, 2012). "Of these, IP-10, IL-6, and TNF-α showed significantly attenuated responses to infection in FP-exposed mice." (PMID 22651370, 2012). "This increased resistance against infection was characterized by augmented levels of bactericidal factors and inflammatory cytokines: ROS, NO, IFNγ TNF IL-6 and IL-12." (PMID 22629382, 2012). "As expected, with the up-regulation of cell surface markers, RB51 infection of WT BMDCs induces a significantly increased production of TNF-α at 24 h post infection (P-value <0.05)." (PMID 22927979, 2012). "In this context, it was interesting to observe that mycobacterial RNA fragments affected the monocyte's ability to control infection despite stimulating TNF-α production." (PMID 22253841, 2012). "TNF-α represents an early phase mediator of inflammation and plays a primary role in the pathogenesis of infection, tissue injury and inflammation as it is suggested by several studies in animals and humans." (PMID 22260184, 2012). "The presumed mechanism for this association suggests that infection downregulates CYP 1A2 by about 90% through increase in circulating IL-6, interferon, and TNF-α." (PMID 22934219, 2012). "In 3d mice, average concentrations of TNF-α were 6-fold lower than WT at 40 h and 2.5-fold lower than WT at 48 h after infection." (PMID 22723955, 2012). "In the experiments presented here, we have shown that naïve or total CD4+ T cells from NFATp−/− mice are impaired in their ability to produce IFN-γ and TNF mRNA and protein in response to MTb infection." (PMID 22844476, 2012). "Our investigations show that the viral gene, ie1, in the context of a natural infection contributes to a significant moderation of TNFα production in multiple organs in vivo." (PMID 22952450, 2012). "Altogether these results show that the production of TNFα can be significantly moderated by an ie1-dependent mechanism in an acute in vivo infection by MCMV." (PMID 22952450, 2012). "The early cytokine responses (TNFα, IL-6, IL-1β, IL-12) were measured on the first day of low-dose or high-dose infection." (PMID 23028333, 2012). "In the following experiments, immune competent BALB/c mice were infected with 3×105 PFU of MCMV or 3×106 PFU of MCMVdie1, and both viral titres and the absolute TNFα response were compared in different organs at days 4 and 7 post-infection." (PMID 22952450, 2012).
infection (continued). "PBMC isolated from WMS calves but not PA calves displayed significantly (p < 0.05) increased TNF secretion on day 2 and 4 post-BHV-1 infection and TNF secretion by the WMS group was significantly greater than the PA group on day 2 and 4 post-BHV-1 infection." (PMID 22435642, 2012). "The infection with BT forms presented earlier production of proinflammatory cytokine TNF-α and later of IFN-γ by both T cells subpopulations." (PMID 22412949, 2012). "Comparison of TNFα levels between MCMV and the MCMVdie3 mutant virus showed that MCMVdie3 infection produces much lower levels of TNFα compared to MCMV infection until 24 hpi." (PMID 22952450, 2012). "It has been demonstrated that CMV can reduce the effects of TNFα by down-regulation of the TNFα receptor during infection and thereby increasing tolerance to extra-cellular TNFα levels." (PMID 22952450, 2012). "Elevated levels of pro-inflammatory cytokines IFN-γ and TNF-α were found at day 5.5 of infection in Il10−/− mice." (PMID 22876184, 2012). "Inflammation is the first response of the immune system to infection or irritation; inflammation is mediated by cytokines such as TNF-α, IL-1β, IL-2, IL-6, and PGE2." (PMID 22919407, 2012). "Regarding TNF-α, infection by MT and BT forms triggered different patterns; in the MT group there is a significant increase at days 14, 28 and 42 by CD8+ T cells and on day 28 by CD4+ T cells." (PMID 22412949, 2012). "In experimental infection by L. major, TNF-α is important for activation of macrophages, in cooperation with IFN-γ, and elimination of intracellular parasites." (PMID 22203861, 2012). "To further explore the mechanisms that can influence the activity of memTNF, we focus on the investigation of spleen macrophages expressing TNF and TNFRs during the infection." (PMID 22666310, 2012). "In our study, we have found an increase of spleen CD4+ T lymphocytes producing IL-10 seven days after infection, in addition to the IFNγ and TNF-α producing cells." (PMID 22666132, 2012). "As observed for the macrophage infections, the East Asian/Beijing and Indo-Oceanic strain lipids (at concentration 0.1 μg and 1.0 μg) induced significantly higher concentrations of TNF-α than those from the Euro-American strains after 24 hours of stimulation." (PMID 21931620, 2011). "Infection triggered an IL-1β, IL-8, and TNF-α response in the mammary gland, while the systemic levels of these cytokines remained unchanged." (PMID 21414189, 2011). "Cases of infection with the gram-positive intracellular pathogen Listeria monocytogenes have been reported for all three first generation TNF antagonists." (PMID 22081766, 2011). "Infection of DCs from each donor (n = 3) with H37Ra consistently stimulated the release of pro- and anti-inflammatory cytokines including TNFα, IL-6, IL-8, IL-10, IL-1β and a modest increase in secretion of IL-12p70." (PMID 22024399, 2011). "TNF-α is detected in the circulation during the erythrocytic phase of the infection in humans and in mice)." (PMID 21394207, 2011). "The monocytes isolated for our ex vivo experiments exhibited low levels of infection but secrete high levels of inflammatory cytokines (TNFα and IL-12 p70) in our hands, signature cytokines secreted by classically activated macrophages." (PMID 21559416, 2011). "Upon systemic infection with T. gondii, IFN-γ and TNF-α mediated responses are upregulated by MIF, and Mif−/− mice are more susceptible to infection presenting increased parasite burden." (PMID 21977228, 2011). "Curiously, the role of IL-1A is to recruit leucocytes in the infection site and to take part, together with TNF-α, in the formation and the maintenance of the granuloma." (PMID 22151930, 2011). "All of these genes were up-regulated in response to Mtb infection and down-regulated by CC-3052 treatment at both 21 and 28 days post-infection, confirming that TNF-α is a target of PDE4 inhibition." (PMID 21364878, 2011).
infection (continued). "Comparable IL-12p70 and IFNγ concentrations were found in the lung of WT mice and Tm-TNF mice 133 days post-infection." (PMID 22132068, 2011). "Upon infection, low levels of TNFα were detected from CD11b+ DCs and more significant levels of IL-12 p70 were detected from CD8α+ DCs." (PMID 21559416, 2011). "Infection with SGB1 Vi− was associated with a significant increase (p<0.05) in the percentage and total cell number of MIP-2, TNF-α, IFN-γ and perforin producing splenocytes cells when compared to similarly stimulated naïve cells." (PMID 21829346, 2011). "Seven days after infection, the cells from the infection control group (S) increased significantly (p < 0.01) the release of IFNγ and TNFα, compared to the untreated control (C)." (PMID 21813005, 2011). "At 7 and 10 weeks post-infection, consistently low TNF-α MFI values were seen in all CD8 T cell subsets." (PMID 22205939, 2011). "The response of EC to several cytokines, especially TNF, has been considered as one of the important determinants of pathology during infection with a number of pathogens." (PMID 22043276, 2011). "We cannot exclude that these monocytes will respond in a similar way as MM, with high percentages of cells infected, a productive infection and the induction of TNF-alpha." (PMID 21731493, 2011). "In this study, we investigated the contribution of two molecular forms of TNF, in particular Tm-TNF in host immunity in mice immunized by prior infection with M. tuberculosis." (PMID 22132068, 2011). "Mice infected with CRM-0019 showed significant reduced numbers of lung and spleen TNFα–expressing CD4+ T cells by day 30 of infection compared to the reference strain." (PMID 21931831, 2011). "Lung sections were obtained from infected WT mice, TNF−/− mice and Tm-TNF mice at the indicated time points post-infection and pulmonary pathology analyzed." (PMID 22132068, 2011). "Infection with the well-encapsulated S. suis wild-type strain 10 and stimulation with the proinflammatory cytokine TNFα led to an augmented PMN traversal in both the presence and absence of IL-8." (PMID 21592385, 2011). "The production of IL-1β, IFN-α, IL-10, TGF-β, IL-4 and TNF-α by the nervous tissues of infected animals increased significantly at different times after infection." (PMID 21813860, 2011). "TNFα (+) cells were significantly (p < 0.01) increased in the infection control group (S) (54 ± 10 cells/10 fields) 7 days post infection, compared with the basal data (31 ± 12 cells/10 fields and 31 ± 11 cells/10 fields for C and Lc groups, respectively)." (PMID 21813005, 2011). "Secretory TNF-α and IL-8 were found to be elevated after challenge with N. meningitidis compared to N. lactamica at 24 hours post infection." (PMID 22028815, 2011). "When we correlated the extracellular CA-p24 levels with the number of CA-p24 producing cells, an increase was observed upon TNFα induction in the cultures infected with 3 ng and 9 ng CA-p24 as viral input for infection." (PMID 21923919, 2011). "During VVΔE3L infection high levels of TNF-α, IFN-β, IFN-α, IL-6 and ISG15 mRNA were detected, which is in accordance with previous publications." (PMID 22174864, 2011). "TNF is a potent proinflammatory cytokine produced early in the innate immune response to infection that promotes a wide range of immunologic responses." (PMID 22172537, 2011). "Collectively, these data suggest that TNF-α secreted early upon infection with the ST-11 isolates is required to sensitize cells to apoptosis in synergy with the late down-regulation of NF-κB transcriptional activity." (PMID 22144896, 2011). "Treatment with ASA early in infection not only ablated TNF-α release from spleen but also increased SOCS-2 and reduced TRAF6 expression." (PMID 21347238, 2011). "Both Interferon gamma (IFNγ) (primarily from NK cells) and tumor necrosis factor alpha (TNFα) are essential for early resistance to infection." (PMID 21559416, 2011).